CTDSPL2 (CTD small phosphatase like 2)
Description:
Serine/threonine phosphatase that promotes gluconeogenesis by dephosphorylating FOXO1 and FOXO3A, promoting their nuclear retention and enhancing their transcriptional activity on PCK1 and G6PC1, key enzymes in hepatic gluconeogenesis. Essential for proper embryonic skeletal development by regulating chondrocyte survival through dephosphorylation of FOXO3 (By similarity). By maintaining FOXO3 in its active, dephosphorylated form, inhibits excessive apoptosis of chondrocytes, which is essential for normal endochondral ossification and cartilage formation (By similarity).
Synonyms: SCP4; HSPC058; HSPC129; FLJ10523
Tractability: PROTAC: ubiquitination databases record sites on it; its protein half-life has been measured.
Gene: Protein-coding gene on chromosome 15 (44,427,599 to 44,529,038, forward strand). Ensembl gene ENSG00000137770.
Subcellular location: Nucleus
Subcellular location (Human Protein Atlas): Nucleoplasm
Gene Ontology:
Molecular function: protein binding; protein serine/threonine phosphatase activity; RNA polymerase II CTD heptapeptide repeat phosphatase activity; phosphatase activity
Biological process: positive regulation of gluconeogenesis; bone development; cartilage development; embryonic skeletal system development; growth plate cartilage chondrocyte growth; regulation of transcription by RNA polymerase II
Cellular component: nucleus
Genetic constraint (gnomAD): Loss-of-function variants: 0 observed, 16.22 expected, observed/expected ratio (o/e) 0, 90% interval 0 to 0.18. The upper end of that interval is the gene's LOEUF score, 0.18, which puts it in group 1 of 6, group 1 being the genes least tolerant of losing a copy. Missense variants: 178 observed, 193.3 expected, observed/expected ratio (o/e) 0.92, 90% interval 0.81 to 1.04. Synonymous variants: 72 observed, 67.53 expected, observed/expected ratio (o/e) 1.07, 90% interval 0.88 to 1.3.
Homologues: Orthologues: chimpanzee CTDSPL2 (99% identical), macaque CTDSPL2 (99% identical), dog CTDSPL2 (99% identical), mouse Ctdspl2 (97% identical), rat Ctdspl2 (97% identical), pig CTDSPL2 (93% identical), rabbit CTDSPL2 (91% identical), guinea pig CTDSPL2 (86% identical), tropical clawed frog ctdspl2 (83% identical), zebrafish ctdspl2a (73% identical), zebrafish ctdspl2b (70% identical), Caenorhabditis elegans scpl-3 (33% identical). Paralogues in human: CTDSPL (23% identical), CTDSP1 (21% identical), CTDSP2 (20% identical), CTDNEP1 (19% identical), TIMM50 (18% identical).
Diseases named in the same sentence as CTDSPL2 in open-access papers:
CTDSPL2 is named in the same sentence as 10 diseases in open-access papers, as found by Europe PMC text mining. Sharing a sentence is not in itself a finding about the gene and the disease. The quoted sentences say what the papers report.
pancreatic cancer (2 papers, 2023 to 2024). "CTDSPL2 has been reported as tumor suppressor, involved in restraining tumor growth in pancreatic cancer." (PMID 37920164, 2023).
acute myeloid leukemia (1 paper, 2024). Acute myeloid leukemia (AML) is a group of neoplasms arising from precursor cells committed to the myeloid cell-line differentiation. "In acute myeloid leukemia (AML), CTDSPL2 dephosphorylates the kinases STK35 and PDIK1L, supporting the proliferation of AML cancer cells and affecting the expression of genes involved in amino acid biosynthesis and transport." (PMID 39209829, 2024).
B-cell lymphomas (1 paper, 2017). "Deep sequencing analysis of viral integration sites has identified CTDSPL and CTDSPL2 as common integration sites in ALV-induced B-cell lymphomas, suggesting a potential role in driving oncogenesis." (PMID 28915671, 2017). "In this report we have identified both CTDSPL and CTDSPL2 as common integration sites in ALV-induced B-cell lymphomas." (PMID 28915671, 2017). "To better characterize the role of CTDSPL and CTDSPL2 in ALV-induced B-cell lymphomas, we generated truncated transcripts in viral vectors to mimic those being expressed in tumors." (PMID 28915671, 2017). "Our lab has previously identified CTDSPL (C-terminal domain small phosphatase-like) and CTDSPL2 (C-terminal domain small phosphatase-like 2) as common integration sites in ALV-induced B-cell lymphomas." (PMID 28915671, 2017).
lentivirus infection (1 paper, 2010). Virus diseases caused by the Lentivirus genus. "We achieved overexpression and repression of the CTDSPL2 gene in CD34+ cells by lentivirus infection." (PMID 20932329, 2010).
lung carcinoma (1 paper, 2024). "CCK8 assay demonstrated that CTDSPL2 overexpression-induced lung cancer cell proliferation was reversed by inhibiting JAK or PI3K." (PMID 39209829, 2024). "However, the role of CTDSPL2 and its regulatory mechanism in lung cancer remain unclear." (PMID 39209829, 2024). "In our animal experiments, a murine lung cancer cell line, LLC, was used to stably deplete CTDSPL2." (PMID 39209829, 2024).
tumor (5 papers, 2017 to 2024). "SC79 treatment partially rescued attenuated tumor growth caused by CTDSPL2 knockdown and such effect was reversed by ruxolitinib combined with SC79 treatment." (PMID 39209829, 2024). "Reports have suggested that CTDSPL2 is implicated in tumor development, with phosphatase activity being a contributing factor." (PMID 39209829, 2024). "Several reports have implicated the involvement of phosphatase activity of CTDSPL2 in tumor development." (PMID 39209829, 2024). "This study investigated the functional role and underlying molecular mechanisms of CTDSPL2 in NSCLC progression after identifying it as a novel target of the tumor suppressor miR-193a-3p." (PMID 39209829, 2024). "The expression of MEIS2, FMN1 and CTDSPL2 proteins is associated with impaired renal function and can be regulated by tRF-5b, which can replace miR-458 during tumor suppression." (PMID 35409004, 2022). "CTDSPL2 has been reported as a tumor suppressor involved in restraining tumor growth in pancreatic cancer." (PMID 38793044, 2024). "By RNA sequencing and TCGA analysis, we found that CTDSPL2 is a novel target gene of the tumor suppressor miR-193a-3p, which has the potential to function as an oncogenic molecule that promotes NSCLC progression." (PMID 39209829, 2024). "In a syngeneic mouse model, we validated that CTDSPL2 knockdown impeded tumor growth and metastasis in vivo." (PMID 39209829, 2024). "Overall, these data suggested that CTDSPL2 significantly enhanced NSCLC tumor growth and metastasis in vivo." (PMID 39209829, 2024). "Next, we used subcutaneous tumor-bearing mice to further confirm the involvement of JAK1/PI3K/AKT axis in CTDSPL2-induced tumor growth." (PMID 39209829, 2024). "This, in addition to the observation that integrations in CTDSPL and CTDSPL2 occur in both primary and secondary tumors, suggests a potential role in promoting tumor metastasis." (PMID 28915671, 2017). "The results confirmed a reduction in CTDSPL2 expression in tumor tissues from the shCTDSPL2 group." (PMID 39209829, 2024). "The expression of CTDSPL2 protein in tumor tissues was examined by western blot analysis." (PMID 39209829, 2024). "CTDSPL2 was identified as a novel target of the tumor suppressor miR-193a-3p." (PMID 39209829, 2024). "The protein expression level of CTDSPL2 was higher in tumor tissues than that in non-tumor tissues." (PMID 39209829, 2024). "CTDSPL2 may influence CD4+ T cell tumor infiltration through additional pathways." (PMID 39209829, 2024). "Interestingly, integrations in CTDSPL and CTDSPL2 frequently occur in the same tumor." (PMID 28915671, 2017). "CTDSPL2 can promote the malignant progression of NSCLC, thereby enhancing tumor growth and metastasis." (PMID 39209829, 2024). "CTDSPL2 knockdown or control cells were subcutaneously injected into C57/BL6 mice and tumor formation was monitored." (PMID 39209829, 2024). "Depletion of CTDSPL2 inhibited the proliferation, migration, and invasion of NSCLC cells, as well as tumor growth and metastasis in mouse models." (PMID 39209829, 2024). "Using the tumor tissues from immune-competent C57/BL6 mice subcutaneously injected with LLC-derived cells, we performed IHC staining to evaluate the influence of CTDSPL2 on T cell recruitment." (PMID 39209829, 2024). "CTDSPL2 may potentially affect T cell infiltration in tumors via JAK1, as previous research has demonstrated the influence of JAK1 on the tumor microenvironment." (PMID 39209829, 2024). "Furthermore, unlike CTDSP1/2/L proteins, CTDSPL2 has not been previously reported to act on pRb, a main tumor suppressor target common to the other 3 members of the family." (PMID 28915671, 2017).
cancer (3 papers, 2017 to 2024). A tumor composed of atypical neoplastic, often pleomorphic cells that invade other tissues. "Carboxy-terminal domain small phosphatase like 2 (CTDSPL2), one of the haloacid dehalogenase phosphatases, is associated with several diseases including cancer." (PMID 39209829, 2024). "Our work suggests that CTDSPL and CTDSPL2 play a role in cancer and seem to have pro-oncogenic characteristics." (PMID 28915671, 2017). "In contrast, there are only few data about CTDSPL2 (also known as SCP4) expression and functions in cancer cells." (PMID 31774910, 2019).
CTDSPL2 also shares sentences with these, for which no sentence is quoted: brain tumor (1 paper); chronic kidney disease (1); glioma (1).